GADD45A (growth arrest and DNA damage inducible alpha)
Diseases named in the same sentence as GADD45A in open-access papers (continued):
Sharing a sentence is not in itself a finding about the gene and the disease.
triple-negative breast carcinoma (6 papers, 2012 to 2024). An invasive breast carcinoma which is negative for expression of estrogen receptor (ER), progesterone receptor (PR), and human epidermal growth factor receptor 2 (HER2). "And it was also mentioned that GADD45A expression levels in triple-negative breast cancer seemed to exhibit good two-point performance on its risk grouping, etc.." (PMID 37259059, 2023). "Patients with triple negative breast cancer might be stratified into high risk and low risk groups based on the GADD45A expression levels." (PMID 30128181, 2018). "Moreover, our study was the first study estimating the prognostic significance of GADD45A in triple negative breast cancer." (PMID 30128181, 2018). "In a previous investigation we demonstrated that the I3C derivative CTet is able to induce autophagy, and to inhibit cell proliferation in estrogen receptor-positive and triple negative breast cancer cell lines through p21/CDKN1A and GADD45A overexpression." (PMID 22905241, 2012). "Kaplan–Meier survival analysis revealed that patients with high GADD45A expression levels had a worse long-term prognosis in triple negative breast cancer (P = 0.041), but it was not an independent prognostic factor in multivariate analysis (P = 0.058)." (PMID 30128181, 2018).
viral infection (6 papers, 2016 to 2025). "We found that in MA-stimulated cells, GADD45A levels were also elevated in the presence of viral infection." (PMID 31796757, 2019).
liver cancer (5 papers, 2006 to 2025). An epithelial or non-epithelial malignant neoplasm that arises from the liver. "For instance, in liver cancer cells, the activation of GADD45A by isocorydine derivatives upregulates p21, which causes G2/M phase arrest and suppresses tumor growth." (PMID 39408228, 2024). "In vivo, TFPI2 overexpression decreased tumor volume in an orthotopic nude mouse liver cancer model, but GADD45A knockdown reversed this effect." (PMID 40765823, 2025).
Sepsis (5 papers, 2014 to 2025). Sepsis is defined as life-threatening organ dysfunction caused by a dysregulated host response to infection. "These efforts aim to incorporate BMX, GRB10, and GADD45A into diagnostic panels and personalized treatment strategies, thereby improving sepsis management and patient outcomes." (PMID 40230692, 2025). "Collectively, these features position BMX, GRB10, and GADD45A as potential key contributors to the interplay of hyperinflammation, immunosuppression, and oxidative stress that underlies sepsis progression." (PMID 40230692, 2025). "We utilized a tagging SNP (tSNP) approach after gene resequencing to study the association of GADD45a gene with sepsis/ALI." (PMID 24940746, 2014). "In conclusion, we used machine learning algorithms to identify 3 key DDR-related genes, GADD45A, HMGB2, and RPS27L, which exhibit a good diagnostic impact on sepsis." (PMID 39889168, 2025). "In conclusion, this study leverages integrated transcriptomics and ML approaches to identify BMX, GRB10, and GADD45A as pivotal biomarkers and therapeutic targets in sepsis." (PMID 40230692, 2025). "Integration of the outputs from all five algorithms identified BMX, GRB10, and GADD45A as the core biomarkers for sepsis, reinforcing their reliability for diagnosis." (PMID 40230692, 2025). "We examined the expression of BMX, GRB10, and GADD45A in sepsis patients, observing significantly elevated expression in sepsis compared to healthy controls." (PMID 40230692, 2025). "GSVA analysis further confirmed the roles of BMX, GRB10, and GADD45A in immune dysregulation during sepsis, highlighting their involvement in immune environment alterations." (PMID 40230692, 2025). "The calibration plots showed that the nomogram model composed of 3 genes, GADD45A, HMGB2, and RPS27L, exhibited good diagnostic prediction for sepsis." (PMID 39889168, 2025). "Despite our robust findings, several limitations must be addressed to fully utilize BMX, GRB10, and GADD45A as sepsis biomarkers and therapeutic targets." (PMID 40230692, 2025). "The chord diagram highlighted BMX, GRB10, and GADD45A’s involvement in reactive oxygen species metabolism, a critical pathway in sepsis." (PMID 40230692, 2025). "In conclusion, this integrated approach provides profound insights into the molecular mechanisms underlying sepsis, pinpointing BMX, GRB10, and GADD45A as pivotal biomarkers and therapeutic targets." (PMID 40230692, 2025). "Due to the limited number of studies, the role of GADD45A in sepsis remained unclear and our study may provide some insights for future study." (PMID 39889168, 2025). "Importantly, we identified 3 pivotal genes, including GADD45A, HMGB2, and RPS27L, which exhibited good diagnostic prediction for sepsis." (PMID 39889168, 2025). "This study has identified 5 key genes – CTSD, GADD45A, MAPK14, MMP9, and VIM – that are significantly upregulated in sepsis patients compared to healthy controls." (PMID 40184094, 2025). "The expression levels of CTSD (P < .001), GADD45A (P < .001), MAPK14 (P < .001), MMP9 (P < .001), and VIM (P < .001) were significantly higher in patients with sepsis than in normal healthy controls." (PMID 40184094, 2025). "Five hub genes including CTSD, GADD45A, MAPK14, MMP9, and VIM were upregulated in patients with sepsis compared with normal controls in the GSE28750 (peripheral blood samples) and GSE64457 (neutrophil samples) datasets." (PMID 40184094, 2025). "Three different expressed DDR-related genes (GADD45A, HMGB2, and RPS27L) were identified as sepsis biomarkers." (PMID 39889168, 2025). "Patients with sepsis had a significantly higher expression of CTSD, GADD45A, MAPK14, MMP9, and VIM than normal health controls." (PMID 40184094, 2025).
bladder cancer (4 papers, 2022 to 2024). "Previous studies have shown that overexpression of GADD45A can cause G2/M cell cycle arrest and reduce proliferation in T24 bladder cancer cells, as well as induce G0/G1 and G2/M phase arrest in EBV+ B lymphoma cells through the activation of the p38 MAPK/TAp73/GADD45A axis." (PMID 39408228, 2024).
cervical carcinoma (4 papers, 2012 to 2023). A carcinoma arising from either the exocervical squamous epithelium or the endocervical glandular epithelium. "And the PI3K/AKT signaling pathway mediated by the downregulation of GADD45A is associated with reduced radiosensitivity in cervical cancer (CC)." (PMID 37259059, 2023). "For example, previous studies have shown that ionizing radiation treatment induces GADD45A expression in cervical cancer and sensitizes cancer cells to radiotherapy." (PMID 35281859, 2022). "Lack of GADD45A induction in cervical carcinomas correlated with a good clinical response to radiotherapy." (PMID 29515153, 2018).
fibrosis (4 papers, 2021 to 2026). the formation of excess fibrous connective tissue in an organ or tissue in a reparative or reactive process. "Gadd45a-null mice with nonalcoholic steatohepatitis show more severe hepatic fibrosis and inflammation." (PMID 33391480, 2021). "Additionally, the genotype distribution differed significantly for rs225014 (DIO2) between groups of patients affected by different stages of HBV-related liver diseases, and between the cirrhosis and fibrosis group for rs532446 (GADD45A)." (PMID 37059745, 2023). "Moreover, both SNPs within the GADD45A gene (rs532446, rs37834688) demonstrated different distributions between cirrhosis and fibrosis groups." (PMID 37059745, 2023).
neuroblastoma (4 papers, 2012 to 2024). Neuroblastoma (NB) is the most common solid, extracranial childhood tumor. "It has been reported that VPA induced upregulation of Gadd45a in neuroblastoma cells stimulates neurite outgrowth." (PMID 22970179, 2012). "In addition, Gadd45a stimulates neurite outgrowth in a neuroblastoma cell culture." (PMID 38473843, 2024). "Treatment of the mouse neuroblastoma cell line, N1E-115, with the HDAC inhibitor, valproic acid (VPA), has been shown to specifically upregulate Gadd45a protein expression and induce neurite outgrowth from these cells via activation of the MAP3K, MEKK4." (PMID 22970179, 2012). "Gadd45a directly binds to and activates the MAP3K, MEKK4, a protein reported to promote neuronal migration in developing cortex and neurite outgrowth in neuroblastoma cells." (PMID 22970179, 2012).
Obesity (4 papers, 2020 to 2025). Accumulation of substantial excess body fat. "For example, a recent study demonstrates that GADD45A deficiency protects mice against high-fat diet-induced obesity." (PMID 40301189, 2025). "GADD45A has also been recently described as a critical regulator of intramuscular fat infiltration, a common feature during ageing, obesity and myopathies associated with muscular dysfunction and sarcopenia." (PMID 40301189, 2025). "Using unbiased transcriptome data analysis, we found that GADD45A is highly expressed in human and mouse SATs and is associated with obesity." (PMID 37807064, 2023). "We found that GADD45A expression is positively associated with subcutaneous fat deposition and obesity in humans and animals." (PMID 37807064, 2023). "Thus, our results confirm that GADD45A deficiency can protect against HFD-induced obesity." (PMID 37807064, 2023). "We found that GADD45A KO mice were resistant to HFD-induced obesity and increased the level of energy metabolism in the organism." (PMID 37807064, 2023). "We demonstrate that GADD45A deficiency induces iWAT browning and protects mice against HFD-induced obesity." (PMID 37807064, 2023). "We demonstrate that GADD45A deficiency induces the inguinal white adipose tissue (iWAT) browning and protects mice against HFD-induced obesity." (PMID 37807064, 2023). "In this study, we found that GADD45A is highly expressed in human and animal SAT and is associated with metabolic diseases such as obesity." (PMID 37807064, 2023). "Among these differentially expressed genes (DEGs), we found that GADD45A is highly expressed in subcutaneous WAT in mice and humans and is associated with obesity." (PMID 37807064, 2023). "We found that GADD45A expression was positively correlated with subcutaneous fat deposition and obesity in humans and fatty animals." (PMID 37807064, 2023). "Our findings provide novel insights into the regulatory mechanism of GADD45A and combating obesity-related metabolic diseases." (PMID 37807064, 2023). "Unbiased transcriptomics data indicate a positive correlation between adipose Gadd45a mRNA level and obesity." (PMID 32719383, 2020). "Among these, the upregulation of GADD45A promotes subcutaneous fat deposition and obesity." (PMID 40535017, 2025). "In this regard, some authors have pointed out that GADD45A modulation might be a suitable therapeutic approach to prevent obesity and diabetes." (PMID 40301189, 2025). "Using unbiased transcriptomics data analysis, we found that Gadd45a mRNA expression was indeed correlated with obesity and may regulate lipid metabolism and brown adipogenesis." (PMID 32719383, 2020). "Also, the impact that GADD45A has on glucose uptake and insulin sensitivity point to that targeting GADD45A might be therapeutically useful to counteract some of the effects contributing to obesity and diabetes." (PMID 40301189, 2025). "Gadd45a knockout mice exhibited enhanced lipolysis, improved energy utilization, and increased resistance to HFD-induced obesity." (PMID 40535017, 2025). "We showed that deletion of GADD45A significantly increases Ucp1 expression and induces iWAT browning, protects mice from HFD-induced obesity, and improves glucose tolerance and insulin sensitivity." (PMID 37807064, 2023). "Furthermore, whether the expression of Gadd45a is correlated to obesity remains unclear." (PMID 32719383, 2020). "Using a Gadd45a-/- mouse model, we showed that compared to wild-type (WT) mice, knockout (KO) mice exhibited subcutaneous fat browning and resistance to high-fat diet (HFD)-induced obesity." (PMID 37807064, 2023). "Using the Gadd45a-/- mice model, we showed that compared with wild-type (WT) littermates, the KO mice exhibit subcutaneous fat browning and attenuate high-fat diet (HFD)-induced obesity." (PMID 37807064, 2023).
Obesity (continued). "Our results demonstrate that GADD45a is a critical regulator of BAT growth and function, and suggest that may be a potential therapeutic target to combat obesity and other metabolic diseases." (PMID 32719383, 2020).
psoriasis (4 papers, 2021 to 2024). An autoimmune condition characterized by red, well-delineated plaques with silvery scales that are usually on the extensor surfaces and scalp. "Rodríguez-Jiménez found that patients with psoriasis had a reduced expression of GADD45a compared to healthy individuals." (PMID 35893255, 2022). "Similar to the findings of RA patients, our data show that lesional skin from psoriasis patients express low levels of GADD45a and GADD45b." (PMID 34272424, 2021). "Flow cytometry analysis confirmed the higher expression of the GADD45a protein in peripheral T lymphocytes from psoriasis in both, unstimulated T cells and TCR-activated T cells." (PMID 34272424, 2021). "Here, we analyzed the expression of GADD45a and GADD45b in the skin, dendritic cells and circulating T cells in a cohort of psoriasis patients and their regulation by inflammatory signals." (PMID 34272424, 2021). "To explore the role GADD45a and GADD45b in psoriasis, we first analyzed the expression of GADD45a and GADD45b genes in lesional and non-lesional skin samples from 30 patients (17 male/13 female) with plaque psoriasis and 15 control subjects (7 male/8 female)." (PMID 34272424, 2021). "Psoriasis patients exhibited a lower expression of GADD45a at the epidermis but a higher expression in dermal infiltrating T cells in lesional skin." (PMID 34272424, 2021). "RT-PCR assays showed that CD4+ T cells from psoriasis patients expressed higher levels of GADD45a compared to control subjects." (PMID 34272424, 2021). "Although the increment of both GADD45a/b molecules at basal conditions in psoriasis may be a consequence of the pro-inflammatory environment, we did not observe any difference in the activation of the p38 pathway compared to controls." (PMID 34272424, 2021). "It is conceivable that the reduction of GADD45a expression in keratinocytes from psoriasis patients could promote keratinocyte hyper-proliferation and the production of pro-inflammatory mediators." (PMID 34272424, 2021). "Our data demonstrate that GADD45a and GADD45b are upregulated in peripheral CD4+ T cells from psoriasis patients at basal conditions." (PMID 34272424, 2021). "Although the expression of GADD45a and GADD45b molecules was diminished in non-stimulated moDCs from psoriasis patients compared to controls, after LPS stimulation both patients and controls were able to upregulate the expression of GADD45a and GADD45b at similar levels." (PMID 34272424, 2021).
acute myeloid leukemia (3 papers, 2009 to 2026). Acute myeloid leukemia (AML) is a group of neoplasms arising from precursor cells committed to the myeloid cell-line differentiation. "More interestingly, we also observed acute myeloid leukemia (AML) in ATM−/− Gadd45a−/− mice." (PMID 24474198, 2014). "Interestingly, ATM−/− Gadd45a−/− mice not only showed a higher incidence of T-cell lymphoma compared to ATM−/− mice, but also developed acute myeloid leukemia (AML)." (PMID 24474198, 2014).
Anxiety (3 papers, 2019 to 2025). Intense feelings of nervousness, tension, or panic often arise in response to interpersonal stresses. "Significantly, based on these findings, we can suggest the participation of the Gadd45a gene in cognition as well as in anxiety-related behavior." (PMID 38473843, 2024). "A large number of behavioral parameters were found to be unaltered compared to wild‐type littermates (Gadd45a‐WT), including locomotion and exploration (Fig EV1A), anxiety (Fig EV1B and C), and depressive‐like behavior (Fig EV1D)." (PMID 30948457, 2019).
esophageal cancer (3 papers, 2017 to 2023). A primary or metastatic malignant neoplasm involving the esophagus. "Reduced expression of GADD45a has been associated with poor survival in esophageal cancer patients." (PMID 28746345, 2017).
esophageal squamous cell carcinoma (3 papers, 2012 to 2025). Esophageal squamous cell carcinoma (ESCC) is a type of esophageal carcinoma (EC) that can affect any part of the esophagus, but is usually located in the upper or middle third. "The methylation status and protein expression of GADD45G are significantly associated with the survival of esophageal squamous cell carcinoma (ESCC) patients, while the expression of GADD45A and GADD45B is not." (PMID 41018072, 2025).
heart failure (3 papers, 2023 to 2025). Inability of the heart to pump blood at an adequate rate to meet tissue metabolic requirements. "In fact, Pdk4 was also reduced in Gadd45a KO mice, and reduced PDK4 activity in cardiac cells is often accompanied by depressed cardiac performance, cardiac hypertrophy and heart failure." (PMID 40301189, 2025). "Indeed, although current research indicates that GADD45A does not present significant sex-related differences in its expression and function, several studies suggest that women and female mice show less inflammation, fibrosis, and apoptosis upon heart failure and cardiac hypertrophy." (PMID 40301189, 2025).
Parkinson disease (3 papers, 2015 to 2024). A progressive degenerative disorder of the central nervous system characterized by loss of dopamine producing neurons in the substantia nigra and the presence of Lewy bodies in the substantia nigra and locus coeruleus. "Intriguingly, parkin overexpression induces Gadd45a expression in vitro suggesting a link between some forms of parkinsonism and this transcript." (PMID 25992874, 2015).
sarcopenia (3 papers, 2016 to 2022). Progressive decline in muscle mass due to aging which results in decreased functional capacity of muscles. "Other studies have found similar results in aged mice, showing Gadd45a and Runx1 are elevated with a KD, which has been shown to mitigate sarcopenia." (PMID 36458175, 2022). "Previous longitudinal data indicates that Gadd45a is elevated in aged mouse skeletal muscle during the transition to sarcopenia, which involves progressive muscle atrophy." (PMID 36458175, 2022).
Stroke (3 papers, 2018 to 2023). Sudden impairment of blood flow to a part of the brain due to occlusion or rupture of an artery to the brain. "It is plausible that stroke mediates stress-induced induction of Gadd45a in a similar manner to disuse, illness, and starvation." (PMID 32629989, 2020). "A recent RNAseq study of the TA muscle using a mouse stroke model in 5 m mice found altered transcriptomes compared to age-matched non-stroke mice including: an upregulation in stroke mice >log2fc1 of Gadd45a, Shroom3, Chrna2, and MuSK, along with downregulation (log2fc < −1) of P2ry1." (PMID 37876943, 2023). "Both Gadd45a and Cdkn1a were significantly upregulated in post-stroke muscle." (PMID 32629989, 2020).